ISL1 (ISL LIM homeobox 1)
Diseases named in the same sentence as ISL1 in open-access papers (continued):
Sharing a sentence is not in itself a finding about the gene and the disease.
tumor (continued). "Tumor size was measured on the indicated days after injection, and the tumor volumes formed by the ISL1-overexpressing cells were significantly larger than that of the control cells at day 21 (1.56 ± 0.73 cm3 vs. 0.35 ± 0.21 cm3, p < 0.05)." (PMID 27183908, 2016). "We demonstrated that ISL1 enhanced tumor growth in vivo and promoted GC cell proliferation, colony formation, and soft agar growth in vitro." (PMID 27183908, 2016). "Concurrent ISL1/HOXA9 methylation in HG-NMIBC reliably predicted tumour recurrence and progression within one year (Positive Predictive Value 91.7%), and was associated with disease-specific mortality (DSM)." (PMID 26332997, 2015). "Conversely, methylation frequency in recurrence and progression tumours in ISL1 was markedly greater than in their low/intermediate-grade counterparts." (PMID 26332997, 2015). "In our HG-NMIBC cohort, HOXA9 or ISL1 methylation at initial diagnosis reliably predicted tumour recurrence or progression within one year." (PMID 26332997, 2015). "We found that the initiation and the growth of tumor were significantly earlier and faster with ISL-1 overexpressing cells than those with the control cells." (PMID 25070240, 2014). "The protein level of ISL-1 in the tumors was positively correlated with the tumor volumes in each group." (PMID 25070240, 2014). "Further, ISL1 downregulation could effectively inhibit tumor growth in a human CRPC xenograft model." (PMID 34753990, 2021). "Moreover, for pancreatic and small intestinal NENs, the two largest subgroups, ISL1 staining results were consistent irrespectively of tumor source and WHO grade." (PMID 32813226, 2020). "Therefore, the ISL1 expression was consistent throughout this Pan-NEN cohort irrespectively of tumor localization and WHO grade." (PMID 32813226, 2020). "Moreover, we constructed Kaplan‐Meier curves for the overall survival (OS), which indicated that patients with ISL1‐positive tumours had a higher OS rate." (PMID 31012189, 2019). "Therefore, we used previously established GC-PDX models to evaluate the effect of ISL1 on tumor growth." (PMID 30674889, 2019). "Furthermore, ISL1 overexpression in MGC803 cells promoted xenograft growth in vivo, while ISL1 knockdown inhibited tumor growth." (PMID 27183908, 2016). "Another research showed that ISL1 promoted tumor cell proliferation and tumorigenesis." (PMID 27835911, 2016). "To investigate whether ISL1 promotes tumor growth in vivo, we used a nude mouse xenograft model to study the impact of ISL1 on GC development." (PMID 27183908, 2016). "In summary, we propose that ISL1 promotes tumor cell proliferation and tumorigenesis." (PMID 27183908, 2016). "The ISL1 genes’ promoter-associated island was more frequently methylated in recurrent and progressive high-grade tumours than their non-recurrent counterparts (60.0% vs. 18.2%, p = 0.008)." (PMID 26332997, 2015). "We further compared the expression of ISL-1 in the tumor tissues isolated from the mice." (PMID 25070240, 2014). "Conversely, the tumor growth was obviously impaired with ISL-1 knockdown cells." (PMID 25070240, 2014). "Therefore, parallel methylation of Hoxa9/Isl1 in HG-NMIBC could be used as a predicted value for tumor recurrence and progression." (PMID 33402862, 2020). "In the present study, we examined whether ISL1 plays a role in GC tumor initiation and progression." (PMID 27183908, 2016). "Conversely, for ISL1, methylation frequency in low/intermediate-grade tumours was lower than described previously by others; however, the methylation frequency increase that is apparent in the recurrence and progression tumours is more consistent with these reports." (PMID 26332997, 2015). "The differential methylation frequency in HOXA9 and ISL1 may relate to several confounders, including the method in this study employed to define tumour methylation, and the relatively few low/intermediate-grade tumours for analyses." (PMID 26332997, 2015).
tumor (continued). "In this study, we revealed several pivotal regulatory TFs (HOXC5, ISL1, VENTX, and OTP) in tumor cells by integrating scRNA-seq and scATAC-seq data and further experimentally validated their roles in tumor growth." (PMID 35853872, 2022). "We identified tumor cell-specific regulatory programs mediated by four key transcription factors (TFs) (HOXC5, VENTX, ISL1, and OTP), and these TFs have prognostic significance in The Cancer Genome Atlas (TCGA) database." (PMID 35853872, 2022). "From the CRC network, only ASCL1 emerged from this analysis, given its different dynamic expression during murine TH-MYCN-driven tumor formation compared to HAND2, PHOX2B, GATA3 and ISL1." (PMID 34638267, 2021). "We next determined the correlation between gene-specific methylation with clinical outcomes within the HG tumour cohort; HOXA9 and ISL1 were assessed as the only genes demonstrating a significant difference in frequency or level of methylation." (PMID 26332997, 2015). "RAM+ cells were governed by ZFP42 and IRF8 maintaining anti-tumor immunity, while RAM- cells controlled by ILF2 and ISL1 promoted metastasis and immune evasion, with RAM- malignant cells enriched in patients over 65 years and associated with immunotherapy resistance." (PMID 42304383, 2026). "The ROS1-specific overexpression of NMNAT2, an enzyme involved in nicotinamide adenine dinucleotide (NAD) synthesis, and ISL1, a crucial transcription factor regulating glycolysis and tumorigenesis, highlight the metabolic dependencies of ROS1+ tumor specimens and cell lines." (PMID 39737401, 2024). "Remarkably, Hand2, Phox2b, Gata3 and Isl1 were highly expressed in both TH-MYCN+/+ early hyperplasia and wild-type ganglia at week 1 and remained at this level in both tissues throughout further tumor development." (PMID 34638267, 2021). "This may be due to the low expression of ISL1 in GES1 and the regulation of phosphorylation is different from tumor cells." (PMID 33962568, 2021). "For both HOXA9 and ISL1, there was a significant increase in the mean level of methylation in the recurrence and progression tumours compared to their no-recurrence counterparts." (PMID 26332997, 2015). "Although the trend of an increase in methylation frequency in recurrence and progression (relative to no-recurrence) tumours was apparent for all genes investigated, this was distinctly more marked for the ISL1 gene." (PMID 26332997, 2015). "To further confirm whether ISL-1 could promote tumor growth in vivo, we used the SCID mice xenograft model to study the impact of ISL-1 on NHL genesis and development." (PMID 25070240, 2014). "Moreover, in recurrent and progressive tumor samples, Isl1 and Hoxa9 are displayed by a remarkably high level of methylation when compared to nonrecurrent tumor samples." (PMID 33402862, 2020). "However, how ISL-1 exerts the role in tumor development is not clear." (PMID 25070240, 2014). "ISL1 and HOXA9 showed significantly higher mean methylation in recurrent and progressive tumours compared to non-recurrent tumours (43.3% vs. 20.9%, p = 0.016 and 34.5% vs 17.6%, p = 0.017, respectively)." (PMID 26332997, 2015). "Mean methylation levels within ISL1 and HOXA9 were significantly higher in recurrence and progression tumours compared to their no-recurrence counterparts (43.3% vs. 20.9%, p = 0.016 and 34.5% vs. 17.6%, p = 0.017, respectively)." (PMID 26332997, 2015). "The lack of correlation in clinicopathological parameters and patient demographics suggest that ISL1 and LHX5 may not be suitable prognostic markers for tumour progression because the expression is relatively high in a significant subset of tumours." (PMID 32158343, 2020). "ISL1, INSM1, and SECG all presented with exceedingly high PPVs concerning the distinction between NENs and non-NENs in the clinical setting, irrespective of WHO grade or tumor origin (primary tumor vs. metastasis)." (PMID 32813226, 2020).
tumor (continued). "Hence, a focally positive or positive ISL1, INSM1, and/or SECG staining (in > 30% of cells, which was the cut-off for focal positivity in the NEN group) is highly indicative of a NEN when the pathologist is facing a non-NEN tumor with a histological suspicion of a NEN." (PMID 32813226, 2020).
cancer (19 papers, 2014 to 2026). A tumor composed of atypical neoplastic, often pleomorphic cells that invade other tissues. "Abnormal expression of insulin gene enhancer-binding protein 1 (ISL1) has been demonstrated to be closely associated with cancer development and progression in several cancers." (PMID 34753990, 2021). "Functionally, ISL1 has been implicated in many important biological pathways, such as tumorigenesis, cell invasion, apoptosis, and cancer immunity." (PMID 35096593, 2021). "The association between aberrant ISL1 expression and cancer progression is being gradually recognized." (PMID 34753990, 2021). "ISL1 serves a major role in multiple tissue types, such as heart, kidneys, skeletal muscle, nervous system, and endocrine organs, and its upregulation is associated with cancer progression and poor prognosis." (PMID 34753990, 2021). "Upregulated expression of Isl1 is present in many cancers including pheochromocytoma, pancreatic, gastrointestinal, lung tumors, bile duct carcinoma, prostate and breast cancers." (PMID 38110859, 2023). "Isl1 collaborates with other transcription factors to determine final cell types, and its upregulated expression is found in various cancers." (PMID 38110859, 2023). "Recently, ISL1 has been reported to play crucial roles in cancer progression, and this is mainly based on an aberrant expression of ISL1." (PMID 34131100, 2021). "Our study showed that ISL2 shared a similar oncogenic role as its family member, ISL1, in other cancers." (PMID 32894165, 2020). "The expression pattern of Islet-1 (ISL1) and LIM homeobox 5 (LHX5) across different cancer stages and grades, as well as the association between the protein expression of these genes and patient demographics and clinicopathological features, were examined." (PMID 32158343, 2020). "Recently, the role of ISL1 in cancer progression has been gradually recognized and is mainly based on aberrant expression." (PMID 30674889, 2019). "Ectopic expression of ISL1 induced cyclin D1, cyclin B, and c-Myc expression in GC cells, which have been previously shown to be involved in cancer cell proliferation in vitro." (PMID 30674889, 2019). "Genes that contribute to the positive regulation of transcription from RNA polymerase II promoter including SMAD family member 4 and ISL LIM homeobox 1 were both down regulated in cancer cells treated with L6 or L7 tomato extract." (PMID 28448505, 2017). "WARS, TMEM2, STEAP4, and ISL1 activated the “pathways in cancer” pathway in IHs." (PMID 36504560, 2022). "Compared with normal tissues, ISL1 is significantly upregulated in various cancers." (PMID 34131100, 2021). "Our study verified the involvement of ISL1 in tumorigenesis and cancer progression of NB, which may help to provide a potential target for NB therapy in the future." (PMID 34131100, 2021). "The expression and DNA methylation of ISL1 in carcinoma has been studied in many tumors." (PMID 33962568, 2021). "Recently, ISL-1 has been found in some types of human cancers." (PMID 25070240, 2014). "Increasing evidences indicate an important role of ISL-1 in the development of some cancers." (PMID 25070240, 2014). "Whether ISL1 also plays a role in the mitosis of cancer cells needs further study." (PMID 34131100, 2021). "All other coding genes LPHN2, EFNA1, ISL1, TRIM29, PAWR, and GOSR2 were differentially up- or downregulated in different cancers." (PMID 36352089, 2022). "Homeobox genes contain Lin-11, Isl-1, and Mec-3 domains (LIM) subfamilies, which are involved in a series of diseases, including various types of cancer." (PMID 34238116, 2021). "Taken together, these data suggest that the ISL1/SETD7 complex directly binds to the ZEB1 promoter to activate its expression in gastric cells, which consequently leads to cancer tumorigenesis in GC." (PMID 30674889, 2019).
cancer (continued). "Insulin gene enhancer binding protein 1 (ISL1) is a LIM homeodomain transcription factor which has been found to be highly expressed in a variety of malignant tumors, but the function of ISL1 in NB has not been fully elucidated." (PMID 34131100, 2021). "ISL1 may act as a positive modulator of EMT, a critical regulator of cancer stem cell (CSC) phenotype." (PMID 34753990, 2021). "In the 164 cases with adjacent noncancerous mucosa from the same section, we observed that ISL1 was more frequently expressed in cancer lesions than in matched noncancerous mucosa samples (56.71% vs. 7.93%, P < 0.001)." (PMID 30674889, 2019). "However, whether ISL-1 has any functional effect on tumorigenesis and how ISL-1 is regulated during cancer development are yet not clear." (PMID 25070240, 2014).
infection (4 papers, 2011 to 2025). The state of being infected such as from the introduction of a foreign agent such as serum, vaccine, antigenic substance or organism. "After 18 days (starting from SKO infection/transfection) of reprogramming, the mRNA levels of cardiac progenitor marker Mesp1, Isl1 and Nkx2.5 were significantly upregulated in the group with mRNA approach when comparing with the retrovirus approach." (PMID 33942933, 2021). "The other MSC and cardiac markers, CD140a, ISL-1, cardiac Troponin-T, CD106, and CD172a did not change expression levels upon infection with ZIKV." (PMID 32941515, 2020).
cardiovascular diseases (2 papers, 2021 to 2023). "Here, we summarize the roles of Isl1 in cardiovascular development and function, and outline its cellular and molecular modes of action, thus providing insights for the molecular basis of cardiovascular diseases." (PMID 34901033, 2021).
adenocarcinoma (1 paper, 2016). A common cancer characterized by the presence of malignant glandular cells. "In the present study, we demonstrate that ISL1 expression was upregulated in 24 GC biopsies (18 poorly differentiated adenocarcinoma, 4 moderately differentiated adenocarcinoma, 2 well-differentiated adenocarcinoma) by immunohistochemistry (IHC) (12 normal gastric tissues were used as the control)." (PMID 27183908, 2016).
central nervous system disorder (1 paper, 2023). A disease involving the central nervous system. "Essential mutations alter enhancer activity through altered binding of key transcription factors (TFs) of embryonic neocortex, including ISL1, POU3F2, PITX1/2, and several SOX TFs, and are associated with central nervous system disorders." (PMID 36791193, 2023).
ISL1 also shares sentences with these, for which no sentence is quoted: rhabdomyosarcoma (3 papers); cardiac disease (2); epilepsy (2); Hodgkins lymphoma (2); lung carcinoma (2); motor neuron disease (2); neuroendocrine carcinoma (2); viral infection (2); acute myocardial infarction (1); adenosquamous carcinoma (1); alopecia (1); alveolar rhabdomyosarcoma (1); amyotrophic lateral sclerosis (1); B-cell lymphoma (1); brain tumor (1); breast tumors (1); calcification (1); cardiac arrest (1); cardiac arrhythmia (1); cardiomyopathies (1); Cardiovascular Malformations (1); CHARGE syndrome (1); Cognitive impairment (1); coloboma (1); colorectal cancer (1); congenital heart defects (1); coronary artery calcification (1); COVID-19 (1); cyst (1); developmental delay (1).
A further 39 diseases each share a sentence with ISL1 in 1 paper.